HGF (hepatocyte growth factor)
Diseases named in the same sentence as HGF in open-access papers (continued):
Sharing a sentence is not in itself a finding about the gene and the disease.
atherosclerosis (continued). "Surprisingly, some markers of atherosclerosis (fractalkine/CX3CL1, CCL8, M-CSF, HGF), T-cell development/activation (CD40L, IL-7, CCL25, IL-2RB, IL-15RA, CD6) and angiogenesis (VEGF-A) were significantly increased only in AD." (PMID 28821884, 2017). "This paradoxical phenomenon between HGF and circulating CD34-positive cell count on atherosclerosis may result from a consumptive reduction of circulating CD34-positive cells." (PMID 29724162, 2018). "Together with the observations of reduced HGF, PDGBF, MAP2K6, and QDPR, these results suggest that the novel Affibody molecule effectively blocks IL17A and attenuates circulating inflammatory markers and other atherosclerosis-associated proteins." (PMID 35282365, 2022). "Our findings indicate that circulating CD34-positive cell levels could determine the influence of HGF on CIMT in elderly Japanese men and can be expected to serve as an effective tool for the clarification of the roles played by HGF and CD34-positive cells in the progression of atherosclerosis." (PMID 29724162, 2018). "HGF/HGFR signaling is activated in angiogenesis, and may be involved in the pathogenesis of atherosclerosis and restenosis; HGFR is expressed on VSMCs isolated from atherosclerotic plaques and it triggers signaling cascades (involving PI3-kinases, Akt, MEK and Erk1/2) mediating migration of VSMCs." (PMID 28659168, 2017). "Only fat mass, among other factors, predicted early atherosclerosis, p = 0.017; IL-12p40 did not predict IMT, HGF and BMR (p = 0.57, 0.09 and 0.59, respectively)." (PMID 31547124, 2019).
osteosarcoma (26 papers, 2003 to 2025). A usually aggressive malignant bone-forming mesenchymal neoplasm, predominantly affecting adolescents and young adults. "The c-Met (MET) proto-oncogene, initially discovered as a tpr-met fusion in a chemically transformed human osteosarcoma cell line, encodes the receptor for hepatocyte growth factor (HGF)." (PMID 41268440, 2025). "The mesenchymal-epithelial transition factor (c-Met), originally identified as a fusion gene in a human osteosarcoma cell line, is a distinct disulfide-linked heterodimer that acts as a receptor tyrosine kinase for hepatocyte growth factor (HGF)." (PMID 29383132, 2017). "MET, a receptor tyrosine kinase proto-oncogene and the specific receptor for hepatocyte growth factor (HGF), plays a critical role in the initiation and progression of osteosarcoma (OS) through sustained pathway activation." (PMID 40599602, 2025). "MACC1 promotes the development of osteosarcoma by regulating the HGF/c-Met pathway and microtubule stability." (PMID 40740230, 2025). "One study examined frozen samples from 87 primary bone and soft tissue tumors and found that osteosarcoma exhibited the highest levels of MET/HGF expression." (PMID 38596618, 2024). "Several investigations have aimed to understand the genetic and functional changes of the HGF/MET pathway in human osteosarcoma, considering its crucial role in regulating cell proliferation and apoptosis in the liver." (PMID 38596618, 2024). "In one study, the expression of bFGF was inhibited by the suppression of ERK1/2 and Akt, which consequently restrained the synthesis and secretion of HGF in the MG-63 osteosarcoma cell line." (PMID 37048074, 2023). "LINC00619 overexpression promotes apoptosis of osteosarcoma cells by targeting hepatocyte growth factor (HGF) and downregulating AKT mRNA expressions and its protein phosphorylation." (PMID 36230902, 2022). "MACC1 can bind to the c-Met promoter and enhance the proliferation of osteosarcoma cells and vascular endothelial cells through the HGF/c-Met signaling pathway." (PMID 35242498, 2022). "MACC1 can bind to the c-Met promoter and enhance the proliferation of osteosarcoma cells and endothelial cells through the HGF/c-Met signaling pathway." (PMID 35242498, 2022). "In a similar way, treatment of osteosarcoma cell lines with PHA-665752 or with a neutralising anti-HGF antibody enhanced the cytotoxic effect of cisplatin." (PMID 33526881, 2021). "In mouse osteosarcoma cell variant FBJ-LL cells, GD1a inhibited HGF-induced motility and scattering by suppressing c-Met phosphorylation." (PMID 34064863, 2021). "It has been reported that HGF promotes RANKL expression via IL-11 secretion in the human osteosarcoma cell line, Saos-2." (PMID 33114380, 2020). "HGF activates both the mitogen and “motogen” machinery in human osteosarcoma cell lines, and this is related to activation of the ERK and Akt pathways." (PMID 26510912, 2015). "HGF was detected in two out of seven clinical specimens of osteosarcomas." (PMID 38596618, 2024). "The results demonstrated significant staining of MET and HGF/SF in osteosarcomas." (PMID 38596618, 2024). "In recent years, several studies have assessed the expression of MET and HGF in osteosarcoma." (PMID 38596618, 2024). "HGF activates both the mitogen and motogen machinery in osteosarcoma cells." (PMID 34064863, 2021). "Although no clinical results have been published yet in pediatric sarcomas, GD2-directed CAR T cells, in combination with either a hepatocyte growth factor (HGF)-targeted neutralizing antibody or doxorubicin, were effective in preclinical Ewing’s sarcoma and osteosarcoma models." (PMID 34572932, 2021). "In 12 osteosarcoma cell lines, the MET/HGF receptor exhibited overexpression, phosphorylation upon HGF stimulation, and full functionality." (PMID 38596618, 2024).
osteosarcoma (continued). "Molecular pathology and cancer biology data suggest that HGF/MET signaling plays a crucial role in the survival, growth, proliferation, metastasis, and drug resistance of osteosarcoma." (PMID 38596618, 2024). "Statins have been reported to inhibit the expression of bFGF, HGF, and TGF-β in osteosarcoma cells through the inhibition of geranylgeranyl pyrophosphate (GGPP) biosynthesis in the mevalonate pathway." (PMID 37048074, 2023). "Overall, the HGF/c- MET pathway is an exciting target and has shown early promise in cancers such as osteosarcoma." (PMID 36034555, 2022). "MDSCs may also contribute to the metastasis of osteosarcoma by forcing T-cell tolerance and releasing TGF-β and hepatocyte growth factor (HGF)." (PMID 39582869, 2024). "Previous studies revealed that inhibitory effects on cell migration and invasion activity in human renal carcinoma cells, osteosarcoma cells, NSCLC cells and TSAIII inhibits HGF to induce metastatic activity in MDA-MB-231 cells were not due to TSAIII cytotoxicity in the dosage range from 2 to 6 μM." (PMID 36612038, 2022). "Osteocalcin is a bone-specific protein localised in the extracellular matrix; Met, the tyrosine kinase receptor for HGF, is not expressed in osteoblasts, but is ectopically expressed in 60% of osteosarcomas." (PMID 12569382, 2003).
Hypertension (25 papers, 2014 to 2025). The presence of chronic increased pressure in the systemic arterial system. "More studies are needed to confirm the diagnostic and prognostic value of serum HGF concentration in several clinical conditions, including arterial hypertension, inflammatory diseases, and renal injury." (PMID 39457546, 2024). "We aimed to determine the association between serum HGF concentration and albuminuria in subjects with optimal blood pressure and subjects with untreated arterial hypertension." (PMID 39457546, 2024). "This study found that serum HGF concentration is associated with albuminuria not only in individuals with untreated arterial hypertension but also in those with optimal blood pressure." (PMID 39457546, 2024). "Evidences show that concentration of serum hepatocyte growth factor is positively associated with hypertension and increased Hgb concentration." (PMID 34874952, 2021). "The association between HGF and hypertension severity has been established in several human studies." (PMID 29208002, 2017). "Additionally, studies have shown a positive correlation between serum hepatocyte growth factor levels and hypertension, potentially increasing the risk of hypertension." (PMID 39850376, 2024). "Therefore, hemoglobin is also found to be positively associated with hypertension and hypertension-associated vascular damage, which is evaluated by hepatocyte growth factor (HGF)." (PMID 33549053, 2021). "HGF levels were negatively associated with disease duration since commencing treatment in POAG samples, indicating a reduction of HGF over time, which may be linked to or independent from treatment for hypertension." (PMID 29482497, 2018). "Excess HGF in the serum is clinically used as an indicator of advanced atherosclerotic lesions, vascular lesions, and hypertension." (PMID 35185854, 2022). "Other studies identified HGF as a possible biochemical index of hypertension-induced vascular damage." (PMID 26818627, 2016). "On the other hand, hepatocyte growth factor (HGF) has been evaluated as a possible biochemical index of hypertension-induced vascular damage." (PMID 26818627, 2016). "We have observed that changes in the levels of VEGF and HGF in cycle 1 correlated with the worst grade of hypertension, proteinuria, and fatigue." (PMID 25047123, 2014). "The analysis showed a significant correlation between change in VEGF and HGF levels in cycle 1 with the worst grades of hypertension, proteinuria, and fatigue." (PMID 25047123, 2014). "This study aimed to determine the association between serum HGF concentration and albuminuria in subjects with optimal blood pressure (OBP) and untreated arterial hypertension (UAH), as well as its association with BP levels, serum glucose levels, and inflammatory markers." (PMID 39457546, 2024). "However, it is reported that the serum HGF levels increase in patients with venous thrombosis, pulmonary hypertension as well as older age and hypertension." (PMID 30594174, 2018). "However, no studies have reported on a correlation between hemoglobin and HGF accounting for hypertension status." (PMID 26818627, 2016). "Hemoglobin is an easily measured parameter; therefore, if it can substitute for HGF as a possible biochemical index of vascular damage due to hypertension, it could serve as an efficient tool for blood pressure control in daily medical practice." (PMID 26818627, 2016). "Since the prevalence of hypertension might play an important role as a vascular impairment factor, the correlation between hemoglobin and HGF should account for hypertension status." (PMID 26818627, 2016). "However, no studies have reported a correlation between hemoglobin and HGF accounting for hypertension status." (PMID 26818627, 2016).
Hypertension (continued). "From multiple linear regression analysis adjustment for known cardiovascular risk factors, significant positive correlation between hemoglobin and HGF was observed in both men (β (parameter estimate) = 32.7, p < 0.001) and women (β = 18.7, p = 0.002) with hypertension." (PMID 26818627, 2016). "However, other studies have reported HGF as a possible biochemical index of vascular damage due to hypertension." (PMID 26818627, 2016). "Since HGF is constitutively produced by human bone marrow and indirectly promotes the growth of undifferentiated hematopoietic cells and erythroid progenitor cells, HGF level should correlate with hemoglobin, particularly when the bone marrow becomes activated by hypertension." (PMID 26818627, 2016). "Since HGF is useful for evaluating hypertension-induced vascular damage, hemoglobin may be beneficial in this regard as well." (PMID 26818627, 2016). "Regarding all the data on kidney damage and the damaging role of arterial hypertension, as well as the results of our study, a question could be raised as to whether serum HGF concentration should be used as a clinical biomarker of early kidney injury alongside the ACR ratio." (PMID 39457546, 2024). "Like HGF, hemoglobin may be a useful indicator to evaluate hypertension-induced vascular damage." (PMID 26818627, 2016). "The serum HGF concentrations were also found to be higher in the subjects with untreated arterial hypertension, although the difference was not significant." (PMID 39457546, 2024). "Among the commonly used medications, dihydropyridine derivatives (ATC: C08CA, 54 users), often used to treat hypertension, were correlated to increased IL-6 levels, whereas glucocorticoids (ATC: R03BA, 26 users) lowered both Basigin and hepatocyte growth factor (HGF) receptor levels." (PMID 25147954, 2014). "In the present study, GCSF, IL8, HGF, MIP1α, TRAIL, and PDGFBB in patients with MD were not influenced by hypertension." (PMID 36175465, 2022).
liver cirrhosis (25 papers, 2006 to 2025). "The univariate logistic regression analysis showed that levels of IL-1α, IL-6, and HGF had influenced liver cirrhosis risk (p < 0.001)." (PMID 26448742, 2015). "An increase of one unit (1 pg/mL) of the IL-1α concentration resulted in 8% increased risk of the liver cirrhosis, an increase of one unit (1 pg/mL) of IL-6 concentration implicated about 5% increased risk, and an increase of one unit (1 pg/mL) of HGF implicated 3% increased risk of liver cirrhosis." (PMID 26448742, 2015). "The mechanism of HGF in liver cirrhosis is complex, and as this is only a preliminary study, further research is needed to confirm these findings and elucidate the underlying mechanisms." (PMID 39457577, 2024). "Due to the exogenous HGF’s short half-life, HGF-BM-MSC seems affordable for treating liver cirrhosis and disease." (PMID 37226279, 2023). "We used Immunofluorescence and confocal microscopy to observe the expression of SDF-1 and HGF in four groups of liver cirrhosis." (PMID 34712665, 2021). "It not only increased the hepatocyte growth factor (HGF) which played an important role in liver regeneration and attenuated development of liver cirrhosis but also increased hydroxyproline that was an indicator for collagen content." (PMID 32382557, 2020). "Because of the ability of HGF to induce hepatocyte proliferation and liver regeneration, HGF has been suggested to be a potential therapeutic agent for liver cirrhosis." (PMID 30083132, 2018). "Based on these findings, they proposed HGF/c-Met gene therapy for the treatment of patients with liver cirrhosis." (PMID 30538805, 2018). "Genetically engineering HGF into BM-MSCs to treat liver cirrhosis would be optimal from both pharmacological and practical perspectives." (PMID 30538216, 2018). "In liver cirrhosis, the function of the spleen is deteriorating and serum HGF protein levels can be elevated in these patients due to overproduction of HGF protein by the spleen." (PMID 26448742, 2015). "In this study, elevation of serum Il-1α, IL6, and HGF levels correlated with the progression of liver cirrhosis." (PMID 26448742, 2015). "A statistically significant positive correlation was found between concentrations of HGF versus concentrations of IL-1α and IL-6 in the group of patients with liver cirrhosis." (PMID 26448742, 2015). "The relationships between HGF and proinflammatory cytokines and stage of liver cirrhosis were also analyzed." (PMID 26448742, 2015). "The effectiveness of HGF in inhibiting liver cirrhosis has been documented by a large body of literature." (PMID 25380300, 2014). "On the other hand, HGF and glucagon are higher only in T2D patients and this confirms that glucagon and HGF play a specific role in glucose production and homeostasis and in the progression of chronic inflammation to liver cirrhosis and cancer, respectively." (PMID 22745767, 2012). "Transplantation of bone marrow MSC in combination with HGF-CNP was seen as an ideal approach for the treatment of liver cirrhosis." (PMID 21526984, 2011). "Downregulation of TGF-β1 expression and inhibition of fibrosis by HGF were noted in a rat model of liver cirrhosis and a mouse model of chronic renal failure." (PMID 17049072, 2006). "However, the effects of ADMSCs, PRP, and rh-HGF on rat liver cirrhosis induced by obstructive cholestasis have been studied in relatively few trials." (PMID 38474368, 2024). "We showed that the concentration of HGF increases with the progression of liver cirrhosis." (PMID 26448742, 2015). "Moreover, significantly higher concentrations of HGF protein were found in patients with Child class C liver cirrhosis compared to patients with Child class A liver cirrhosis (p < 0.05)." (PMID 26448742, 2015). "Moreover, significantly higher concentrations of HGF were found in the group of patients with class C liver cirrhosis compared to the group of patients with liver cirrhosis A (p < 0.05)." (PMID 26448742, 2015).
liver cirrhosis (continued). "Serum HGF protein levels in Child class C were significantly higher than those in Child class A or B, indicating that these levels can indicate the severity of liver dysfunction in liver cirrhosis." (PMID 26448742, 2015). "Firstly, we can speculate that the lower efficacy of the HGF in inhibiting liver cirrhosis is due to disruption of downstream HGF signaling pathway that conveys the hepatoprotective and antifibrotic effects." (PMID 25380300, 2014). "Transplantation of bone marrow MSC in combination with HGF-CNP could be an ideal approach for the treatment of liver cirrhosis." (PMID 21526984, 2011). "In more detail, levels of the pro-inflammatory mediators CRP, tPA, IL-6, IL-8, HGF, M-CSF, IL-2Ra, IP-10, and MIP-1a were significantly increased in patients with decompensated liver cirrhosis compared with healthy controls." (PMID 41028194, 2025). "In our research, we found that Treg promoted the IDO signaling pathway of hAMSC by secreting TGF-β, thereby secreting more cytokines such as HGF and SDF-1 and reducing the damage of liver cirrhosis." (PMID 34712665, 2021). "We examined the localisation of the transplanted BM-MSCs with enhanced HGF expression in liver tissues and compared their therapeutic efficacy with that found in four other experimental groups to determine whether HGF-modified BM-MSCs could improve liver cirrhosis in rats." (PMID 30538216, 2018). "There was significant positive correlation between HGF, IL6, IL-1α, and stage of liver cirrhosis (p < 0.001) (–8)." (PMID 26448742, 2015). "MMPs more particularly the MMP2 that promote the degradation of ECM in liver cirrhosis should have been secreted by MSC, which in the presence of HGF exhibited increased MMP2 activity, as observed by enhanced fibrolysis and/or prevention of collagen synthesis." (PMID 21526984, 2011). "The present study concluded that therapy with PRP or rh-HGF alone did not result in substantial hepatoprotection in the rat BDL model of liver cirrhosis." (PMID 38474368, 2024). "Treatment with PRP or rh-HGF alone did not yield significant hepatoprotection in the BDL-induced liver cirrhosis model." (PMID 38474368, 2024). "The detailed analysis demonstrated significantly higher HGF concentrations in patients with Child class B and Child class C liver cirrhosis as compared to the control group and alcoholics without liver cirrhosis." (PMID 26448742, 2015). "In rats with liver cirrhosis, HGF suppressed the increase of transforming growth factor-β1 (TGF-β1), which plays an essential role in the progression of liver cirrhosis, decreased profibrogenic markers as collagen expression and α-SMA and inhibited fibrogenesis." (PMID 25380300, 2014).